ALB (albumin)
Diseases named in the same sentence as ALB in open-access papers (continued):
Sharing a sentence is not in itself a finding about the gene and the disease.
esophageal squamous cell carcinoma (44 papers, 2015 to 2025). Esophageal squamous cell carcinoma (ESCC) is a type of esophageal carcinoma (EC) that can affect any part of the esophagus, but is usually located in the upper or middle third. "This study demonstrates the prognostic value of the preoperative albumin-to-fibrinogen ratio (AFR) in predicting postoperative length of stay (LOS) in patients with locally advanced esophageal squamous cell carcinoma (ESCC) following neoadjuvant therapy." (PMID 40730677, 2025). "This study examined the prognostic effects of the adapted systemic inflammation score (aSIS), calculated from serum albumin and the lymphocyte‐to‐monocyte ratio, in a large cohort of 509 esophageal squamous cell carcinoma (ESCC) patients." (PMID 34585051, 2021). "This study aimed to explore the significance of preoperative levels of squamous cell carcinoma antigen (SCC-Ag) and albumin on the cancer-specific survival (CSS) of patients with stage T1-3N0M0 in esophageal squamous cell cancer (ESCC)." (PMID 32456707, 2020). "It was reported that the fibrinogen/albumin ratio was a novel blood tool of cancer prognosis in esophageal squamous cell carcinoma recently." (PMID 30027102, 2018). "The purpose of this study was to evaluate a novel prognostic scoring system—DA score (combination of preoperative plasma D-dimer and serum albumin levels)—and analyze the association between survival of patients with esophageal squamous cell carcinoma (ESCC) and their Glasgow prognostic score." (PMID 26754834, 2016). "The weekly regimen of cisplatin and albumin-bound paclitaxel combined with radiotherapy has been shown to be safe with manageable toxicity and good antitumor activity in patients with locally advanced esophageal squamous cell carcinoma." (PMID 40963872, 2025). "One of these studies demonstrated that combined D-dimer and albumin levels may be used as prognostic markers for esophageal squamous cell carcinoma and nasopharyngeal carcinoma." (PMID 34239566, 2021). "This study was designed to observe the efficacy and safety of albumin-bound paclitaxel plus nedaplatin as neoadjuvant therapy in patients with esophageal squamous cell carcinoma (ESCC)." (PMID 36862884, 2023). "This study aimed to evaluate the prognostic significance of the pretreatment platelet to albumin ratio (PAR) in esophageal squamous cell carcinoma (ESCC) patients undergoing definitive radiotherapy." (PMID 35241740, 2022). "The patient diagnosed as lung adenocarcinomas (LADC) and esophageal squamous cell carcinoma (ESCC), was treated with albumin-bound paclitaxel, nedaplatin, and anti-programmed death 1 (anti-PD-1)." (PMID 40028319, 2025). "This study aimed to explore the association between dietary antioxidant index (DAI) combined with serum albumin-to-globulin ratio (AGR) and postoperative Health-related quality of life (HRQOL) in patients with esophageal squamous cell carcinoma (ESCC)." (PMID 39917166, 2025). "This study aimed to investigate the effect of preoperative albumin-to-globulin ratio (AGR) on overall survival (OS) and health-related quality of life in patients with esophageal cell squamous carcinoma (ESCC)." (PMID 37055773, 2023). "We initially proposed a novel inflammation-based prognostic index, named neutrophil lymphocyte ratio/albumin ratio (NLR/Alb), for predicting the postoperative survival in esophageal squamous cell carcinoma (ESCC)." (PMID 29262582, 2017). "Similarly, in esophageal SCC, serum levels of SCC antigen and albumin have been used to predict patient survival." (PMID 39925577, 2025). "Preoperative serum SCCA and albumin levels can predict survival of esophageal SCC patients with stage T13N0M0, and patients with high SCCA and low albumin levels may have a poor survival outcome." (PMID 35626221, 2022). "This study retrospectively investigated the prognostic significance of the preoperative albumin-globulin score (AGS) and albumin/globulin ratio (AGR) in esophageal squamous cell carcinoma (ESCC)." (PMID 27105522, 2016).
esophageal squamous cell carcinoma (continued). "Upon multivariate analysis of patients with locally advanced esophageal squamous cell carcinoma treated with definitive CRT, the serum albumin level <3.5 g/dL and endoscopic non-traversability were significant negative factors of survival." (PMID 29390576, 2017).
head and neck cancer (44 papers, 2009 to 2025). A primary or metastatic malignant neoplasm affecting the head and neck. "In head and neck cancer, low albumin levels have been linked to reduced quality of life, lower treatment success, and poorer local control rates." (PMID 40941722, 2025). "Moreover, albumin oxidation is associated with pulmonary metastasis in a cohort of head and neck cancer patients." (PMID 30504805, 2018). "Here the authors show plasma redox imbalance caused by albumin oxidation to induce inflammation-independent NETosis and lung metastasis, and albumin oxidation and reduced plasma free thiol to be associated with lung metastasis in a cohort of head and neck cancer patients." (PMID 30504805, 2018). "In head and neck cancer individuals undergoing surgery, a low serum albumin level is indicative of a higher likelihood of postoperative complications and an unfavorable prognosis." (PMID 39979915, 2025). "Although nutritional risk screening scores typically do not include blood values due to high variability, some factors like albumin seem to be surrogate markers for the nutritional status of a head and neck cancer patient." (PMID 39335110, 2024). "Previous study has shown that the levels of serum protein and albumin significantly decreased in head and neck cancer patients who were treated with radiotherapy." (PMID 36824406, 2023). "PNI, a composite index formed by ALC and albumin, has been proven to be related to the prognosis of advanced head and neck cancer treated with ICI." (PMID 37836573, 2023). "Subgroup analysis showed that the C-reactive protein-to-albumin ratio is a significant prognostic marker for various head and neck cancers." (PMID 33652976, 2021). "An elevated pretreatment C-reactive protein-to-albumin ratio predicts a worse prognosis for patients with head and neck cancers." (PMID 33652976, 2021). "On the other hand, the modified Glasgow Prognostic Score (mGPS), a combination of albumin and the CRP level, was also reported to be associated with cancer cachexia and the prognosis in unresectable locally advanced head and neck cancer patients." (PMID 33531609, 2021). "This meta-analysis explored the prognostic value of the C-reactive protein-to-albumin ratio in head and neck cancers." (PMID 33652976, 2021). "Among the study cohort of 112 patients with advanced head and neck cancer who underwent immunotherapy, we identified 99 patients who had albumin and absolute lymphocyte count." (PMID 34830929, 2021). "A phase I study of patients with head and neck cancers has shown that a cisplatin-albumin complex, either at a starting dose of 100 mg/m2 or a gradually escalated dose to 650 mg/m2, caused no significant nephrotoxicity or ototoxicity." (PMID 30189620, 2018). "Several studies have investigated the importance of serum albumin level in postoperative wound infection among patients who have undergone head and neck cancer resection and simultaneous free tissue transfer." (PMID 29576961, 2018). "Only a few studies have focused on clinical impact on the level of serum albumin in head and neck cancer patients." (PMID 29576961, 2018). "Additionally, there is limited high-quality research specifically addressing certain aspects, such as the role of IGF-I or ischemia-modified albumin in head and neck cancer surgery." (PMID 40507441, 2025). "Serum albumin levels are also considered prognostic factors in head and neck cancers." (PMID 40909092, 2025). "Several studies have reported that a lower serum ALB value was linked to a shorter DFS and OS in a variety of cancers, however, only a few studies have focused on the clinical impact on the level of serum albumin in head and neck cancer patients." (PMID 36531036, 2022). "Other studies suggest that a low serum albumin level may be a prognostic factor for 1-year mortality and postoperative complications in patients with head and neck cancer." (PMID 35276861, 2022).
head and neck cancer (continued). "On the basis of these study results, the primary tumor site, cancer stage, age distribution of the study cohort, and albumin physiological decrease with aging may all account for the different cutoffs of CAR in head and neck cancer patients." (PMID 32587804, 2020). "However, the role of the C-reactive protein-to-albumin ratio in other head and neck cancers remains unclear." (PMID 33652976, 2021). "In a study on head and neck cancer patients, age, TNM tumor stage, functional class, systolic and diastolic blood pressure, BMI, and serum albumin concentration were evaluated as predictors of survival." (PMID 21176210, 2010). "Albumin and eGFR baseline were statistically (but not clinically relevant) significantly higher in head and neck cancer patients (median: 42 vs. 41 mmol/L; 94.3 vs. 92.2 mL/min/1.73 m2, respectively)." (PMID 34834585, 2021). "Similarly, some reports have investigated the impact of serum albumin and CRP on the outcome of combination chemoradiotherapy in cases of unresectable head and neck cancers." (PMID 33482792, 2021).
autoimmune disease (43 papers, 2016 to 2025). A disorder resulting from loss of function or tissue destruction of an organ or multiple organs, arising from humoral or cellular immune responses of the individual to their own tissue constituents. "Meanwhile, TGF is closely linked to immunoglobulin-related medical conditions such as autoimmune diseases compared to serum albumin levels." (PMID 37373863, 2023). "Instead of merely correcting low albumin levels, it is crucial to treat underlying autoimmune diseases." (PMID 37400755, 2023). "This analysis showed that serum albumin levels (P = 0.003), C-reactive protein concentrations (P = 0.012), and autoimmune diseases (P = 0.047) were associated with acute postoperative infection." (PMID 36684164, 2022). "Of note, previous studies have shown that low serum BIL and ALB levels are associated with various autoimmune diseases, such as neuromyelitis optica, multiple sclerosis, myasthenia gravis, and anti-N-methyl-d-aspartate receptor encephalitis." (PMID 33329359, 2020). "Its impact on immunity was reflected by associations with albumin/globulin ratio (p = 6e−10), inflammatory bowel disease (p = 2e−9), and pediatric autoimmune diseases (p = 6e−7)." (PMID 32698485, 2020). "Funnel plots and Egger's tests did not suggest a publication bias for the majority of the risk factors examined with the exception of autoimmune disease, albumin, or chemotherapy." (PMID 28938676, 2017). "The cisplatin group also showed increased total protein, likely due to dehydration or stress-related protein accumulation, while serum albumin and globulin levels were elevated, potentially indicating autoimmune disease or cancer." (PMID 40566587, 2025). "Other ratios such as the PLR and CRP/albumin ratio have been reported to be altered in autoimmune disorders, including systemic sclerosis." (PMID 41464713, 2025). "Elevated B12 is an early warning indicator of increased short-term mortality, independently of age, gender, BMI, ICU admission, albumin level, and the presence of solid cancer or autoimmune disease in patients admitted to an internal medicine department." (PMID 38146346, 2023). "Group 2 consisted of 32 samples with albumin, elevated bilirubin, cholesterol, rheumatoid factor, and some other antibodies that exist in the blood for active syphilis or autoimmune diseases." (PMID 35746682, 2022). "Serum albumin (S-Alb) is a widely used biomarker of nutritional status and disease severity in patients with autoimmune diseases." (PMID 27684858, 2016). "An abnormal albumin-to-globulin ratio is connected with autoimmune diseases and liver problems." (PMID 32853226, 2020). "Elevated albumin levels and a prominent complement system presence in centenarians' blood proteome may contribute to resistance to autoimmunity, highlighting potential protective mechanisms against autoimmune diseases in extreme longevity." (PMID 40546301, 2025). "FcRn binding and recycling of IgG and albumin have been exploited to develop therapeutic strategies for enhanced drug delivery, such as Fc or albumin conjugated with viral antigens for efficient delivery of vaccines or to block IgG recycling to improve treatments of autoimmune diseases." (PMID 38607033, 2024). "Hence, to determine whether BPPV is an autoimmune disease, further studies are needed to reveal the association between serum levels of BIL and ALB, and the pathogenesis of BPPV." (PMID 33329359, 2020). "Albumin, the most abundant protein in plasma, serves as a circulating depot for endogenous and exogenous compounds; however, viral infection, malignancies and autoimmune diseases lead to excessive production of immunoglobulins, which raise the level of gamma gap independent of albumin." (PMID 29416697, 2018). "In central nervous system autoimmune diseases such as anti-N-methyl-D-aspartate receptor encephalitis and neuromyelitis optica (NMO), patients tend to have significantly lower serum albumin levels than healthy controls." (PMID 36870949, 2023).
autoimmune disease (continued). "Growing evidence shows that there is a significant relationship between low serum ALB and TBIL levels and autoimmune diseases, which was consistent with our finding that decreased serum ALB and TBIL level was associated with migraine." (PMID 35959386, 2022). "This study investigated the IgA antibodies targeting bovine serum albumin (BSA) in 27 adult celiac disease (CD) patients adhering to a gluten-free diet (GFD), compared to 123 controls (including individuals with autoimmune disorders, those with gastrointestinal cancers, and healthy donors)." (PMID 40507813, 2025). "Patients with autoimmune disease had lower serum albumin levels and higher UPCRs compared to those without autoimmune disease (p = 0.005 and p = 0.019, respectively)." (PMID 36766619, 2023). "Furthermore, clinical data on other ratios like the aspartate transaminase (AST)-to-alanine transaminase (ALT) ratio, ESR/CRP ratio, and CRP/albumin ratio, which have been analyzed in autoimmune diseases, are still lacking in SSc to the best of our knowledge." (PMID 41464713, 2025). "These include antibodies specific to autoimmune diseases, e.g., anti-thyroid peroxidase (anti-TPO), anti-thyroglobulin (anti-TG), and antinuclear antibodies (ANAs), as well as those that are non-specific, such as anti-malondialdehyde-modified human serum albumin (anti-HSA-MDA) or anti-α-crystallin." (PMID 40943118, 2025). "Second, potential confounding factors affecting serum albumin and CRP levels, such as infections and autoimmune diseases, were not assessed." (PMID 37816855, 2023). "Univariable logistic regression identified multiple factors associated with early-onset PDAP compared to no PDAP, including smoking status, autoimmune disease, baseline SBP, serum albumin, TC, SII, NLR, 6-month lymphocyte, 6-month albumin, 6-month CONUT score, and CONUT score change (p < 0.1)." (PMID 41459072, 2025).
injury (43 papers, 2013 to 2026). Damage inflicted on the body as the direct or indirect result of an external force, with or without disruption of structural continuity. "The findings of a study conducted on critically ill patients with traumatic brain injury indicated that fluid resuscitation using albumin was associated with higher mortality rates compared to resuscitation with saline solution." (PMID 40773463, 2025). "Subgroup analysis revealed a possible association between the use of albumin and increased mortality in patients with traumatic brain injury." (PMID 23514431, 2013). "In addition to the impact of albumin on kidney function, higher Cr at the time of admission has been noted to be associated with persistent kidney injury and worse outcomes including higher mortality." (PMID 39518516, 2024). "Decreased albumin levels and increased neutrophil levels provide a biochemical signal of subclinical damage, and their role as early markers of kidney injury should be investigated further in future prospective studies." (PMID 40342889, 2025). "On June 29, 2024, an advanced search on the WHO ICTRP, using “traumatic brain injury” as the condition term and “albumin OR fluid” as the intervention term, yielded 10 trials that were either recruiting or not recruiting." (PMID 39336939, 2024). "It demonstrated that patients with traumatic brain injury had significantly higher mortality in the albumin group." (PMID 37218881, 2023). "The European Society of Intensive Medicine (ESICM) recommends avoiding the use of albumin in neurosurgery, while the Scandinavian guidelines still recommend the use of albumin (20%) in patients with severe traumatic brain injury." (PMID 37218881, 2023). "In contrast, shikonin treatment in the gentamicin-induced kidney injury group significantly reduced the increased urinary albumin and calcium in a dose-dependent manner." (PMID 37237729, 2023). "Injury level, American Spinal Injury Association Impairment Scale (AIS) grade, admission hemoglobin (Hb), platelet to lymphocyte ratio, and neutrophil percentage to albumin ratio (NPAR) were independently associated with ARF onset." (PMID 34346037, 2022). "A predefined subgroup analysis of the ‘Comparison of Albumin and Saline for Fluid Resuscitation in the Intensive Care Unit’ (SAFE) study suggested that albumin should be avoided in patients with traumatic brain injury." (PMID 36329266, 2022). "Although the volume of various blood transfusions was comparable between groups, the patient with kidney injury received an infusion with higher albumin content (P < 0.01)." (PMID 33072437, 2020). "• A hypotonic albumin solution should be avoided as a resuscitation fluid in patients with traumatic brain injury, based on the results of the SAFE subgroup analysis." (PMID 25042164, 2014). "Based on the SAFE trial, albumin and crystalloids appear to have equal effects on mortality in critically ill patients, with the exception of patients with traumatic brain injury." (PMID 23514431, 2013). "And thirdly, patients with traumatic brain injury are frequently hyper-metabolic and hyper-catabolic; demonstrate many aspects of acute phase response, and often have depressed albumin concentration on admission and throughout much of their course of admission." (PMID 34595082, 2021). "With respect to secondary outcomes, our investigation did not support association of hyperoncotic albumin with increased risk of liver injury, in-hospital mortality, or ICU length of stay." (PMID 30564306, 2018). "Furthermore clinical trials will have to show if plasma-specific adverse events like “transfusion-related acute lung injury (TRALI)” or “transfusion-related immune modulation (TRIM)” would be less frequent under treatment of purified plasma-derived components like CFCs or albumin." (PMID 33836790, 2021).